RECQL (RecQ like helicase)
Description:
DNA helicase that plays a role in DNA damage repair and genome stability. Exhibits a Mg(2+)- and ATP-dependent DNA-helicase activity that unwinds single- and double-stranded DNA in a 3'-5' direction. Full-length protein unwinds forked DNA substrates, resolves Holliday junctions, and has DNA strand annealing activity. Plays a role in restoring regressed replication forks. Required to restart stalled replication forks induced by abortive topoisomerase 1 and 2 lesions. Does not unwind G-quadruplex DNA. May play a role in the repair of DNA that is damaged by ultraviolet light or other mutagens.
Synonyms: RecQ1; RECQL1; RECON
Tractability: Small molecule: a structure with a bound ligand is known; it belongs to a druggable protein family. PROTAC: ubiquitination databases record sites on it; its protein half-life has been measured; a small molecule that binds it is known.
Target class: Enzyme
Gene: Protein-coding gene on chromosome 12 (21,468,910 to 21,501,669, reverse strand). Ensembl gene ENSG00000004700.
Subcellular location: Nucleus
Subcellular location (Human Protein Atlas): Nucleoplasm
Gene Ontology:
Molecular function: 3'-5' DNA helicase activity; ATP hydrolysis activity; DNA helicase activity; DNA/DNA annealing activity; double-stranded DNA helicase activity; protein binding; ATP binding; helicase activity; nucleic acid binding
Biological process: replication fork processing; DNA repair; DNA replication; DNA recombination
Cellular component: membrane; nucleoplasm; nucleus; chromosome; cytoplasm
Genetic constraint (gnomAD): Loss-of-function variants: 57 observed, 57.55 expected, observed/expected ratio (o/e) 0.99, 90% interval 0.8 to 1.24. The upper end of that interval is the gene's LOEUF score, 1.24, which puts it in group 5 of 6, group 1 being the genes least tolerant of losing a copy. Missense variants: 582 observed, 657.79 expected, observed/expected ratio (o/e) 0.88, 90% interval 0.83 to 0.95. Synonymous variants: 203 observed, 214.93 expected, observed/expected ratio (o/e) 0.94, 90% interval 0.84 to 1.06.
Gene-disease validity (ClinGen):
ClinGen rates the evidence that RECQL causes each of these diseases.
hereditary breast carcinoma (autosomal dominant): Disputed. Breast carcinoma that has developed in relatives of patients with history of breast carcinoma.
familial ovarian cancer (autosomal dominant): No Known Disease Relationship. An instance of ovarian cancer that is caused by an inherited modification of the individual's genome.
Homologues: Orthologues: chimpanzee RECQL (99% identical), macaque RECQL (98% identical), pig RECQL (90% identical), rabbit RECQL (90% identical), guinea pig RECQL (90% identical), dog RECQL (88% identical), mouse Recql (85% identical), rat Recql (83% identical), tropical clawed frog recql (70% identical), zebrafish recql (54% identical), Caenorhabditis elegans K02F3.12 (43% identical). Paralogues in human: BLM (35% identical), RECQL5 (27% identical), WRN (27% identical), RECQL4 (22% identical).
Diseases named in the same sentence as RECQL in open-access papers:
RECQL is named in the same sentence as 74 diseases in open-access papers, as found by Europe PMC text mining. Sharing a sentence is not in itself a finding about the gene and the disease. The quoted sentences say what the papers report.
breast cancer (39 papers, 2014 to 2025). A primary or metastatic malignant neoplasm involving the breast. "We focused on Polish founder mutations in BRCA1, BRCA2, PALB2, CHEK2, NBN and RECQL (18 alleles), which account for one-half of Polish breast cancer families." (PMID 40770660, 2025). "Recent molecular diagnostic studies have identified RECQL as an important breast cancer susceptibility gene, similar to BRCA1, BRCA2, and PALB2." (PMID 38439896, 2024). "TP-dependent DNA helicase Q1 (RECQL) is a breast cancer susceptibility gene with possible familial links." (PMID 38439896, 2024). "We also found that patients with RECQL mutations were more likely to have a family history of other tumors, particularly breast cancer (52.00% vs. 37.31%; 38.00% vs. 20.27%), than patients without RECQL mutations." (PMID 38439896, 2024). "Taken together, the data supports the view that RECQL deficiency in breast cancer leads to genomic instability and immune infiltration." (PMID 38134458, 2023). "In sporadic invasive breast cancers (IBC), we demonstrated that RECQL deficiency at the transcriptomic and proteomic levels are associated with aggressive breast cancer phenotypes and poor patient survival." (PMID 38134458, 2023). "We conclude that RECQL loss is an early event in breast cancer and promote immune cell infiltration." (PMID 38134458, 2023). "In relation to this, it has been reported by 2 laboratories that heterozygous mutations of RECQL are associated with an increased risk of breast cancer, although this association has been disputed by several other groups." (PMID 35025765, 2022). "Three other studies have investigated the association between RECQL protein or mRNA levels and breast cancer survival." (PMID 35712517, 2022). "To investigate this association further, we measured the RECQL protein levels in tumours from 933 breast cancer patients by immunohistochemistry (IHC) and analyzed their 15-year survival." (PMID 35712517, 2022). "The current body of evidence suggests that higher RECQL protein levels are associated with higher survival rates among breast cancer patients with ER-positive tumours." (PMID 35712517, 2022). "The second study also observed that among 774 breast cancer patients, lower mRNA levels of RECQL were associated with poor distant recurrence-free survival (HR: 2.77, p-value <0.001) and disease-specific survival (HR: 3.10, p-value <0.001)." (PMID 35712517, 2022). "RECQL was first identified as a novel breast cancer susceptibility gene in 2015, by two independent research groups." (PMID 35320498, 2022). "The first study showed that in separate cohorts of 848 and 1977 breast cancer patients, lower protein and mRNA levels of RECQL were associated with worse prognosis; further analysis revealed that this association only held among the ER-positive patients." (PMID 35712517, 2022). "Among unselected breast cancer patients medium/low levels of RECQL protein were associated with inferior disease-specific survival." (PMID 35712517, 2022). "We analyzed the association between RECQL protein levels and breast cancer survival among 933 breast cancer patients diagnosed from 1987 to 1999 in Toronto, Canada." (PMID 35712517, 2022). "To validate this association, we measured the RECQL protein levels in tumours of 933 breast cancer patients using immunohistochemistry analysis and followed the patients for death from breast cancer." (PMID 35712517, 2022). "RECQL (also known as RECQ1 and RECQL1) is a gene of recent interest in breast cancer and an association between high levels of RECQL protein in breast cancer tumour cells and good survival of patients has been reported." (PMID 35712517, 2022). "Each BCSG was associated with at least three diseases except BARD1 and RECQL, which were only associated with breast cancer." (PMID 33959510, 2021). "A recent study found a moderate risk of breast cancer in African American women with RECQL mutation." (PMID 33959510, 2021).
breast cancer (continued). "In the current study, we evaluated the frequency of 20 recurrent mutations in six genes (BRCA1, BRCA2, CHEK2, PALB2, NBN and RECQL) in 165 men diagnosed with breast cancer in Poland." (PMID 34461861, 2021). "On the other hand, RECQL was first identified as a novel breast cancer susceptibility gene in 2015, by two independent research groups." (PMID 33959510, 2021). "We estimated the prevalence of 20 alleles in six genes (BRCA1, BRCA2, CHEK2, PALB2, NBN, RECQL) in 165 Polish male breast cancer patients." (PMID 34461861, 2021). "Twenty founder alleles in BRCA1, BRCA2, CHEK2, NBN, PALB2 and RECQL genes are responsible for the majority of hereditary breast cancers in Polish women." (PMID 34461861, 2021). "In independent studies, damaging mutations in RECQL have been related to increased breast cancer risk and to genomic instability." (PMID 32957588, 2020). "Here, we investigated the contribution of pathogenic RECQL germline variants to hereditary breast cancer in early-onset and familial breast cancer patients from Pakistan." (PMID 33342430, 2020). "The RecQ Like Helicase (RECQL) gene has previously been shown to predispose to breast cancer mainly in European populations, in particular to estrogen receptor (ER) and/or progesterone receptor (PR) positive tumor." (PMID 33342430, 2020). "The goal of the current study was to estimate the prevalence of twenty alleles in six genes, BRCA1/2, CHEK2, PALB2, NBN, and RECQL, in Polish early-onset breast cancer patients." (PMID 32824581, 2020). "Overall, these findings suggest a controversial role of RECQL as a breast cancer susceptibility gene." (PMID 33342430, 2020). "Our data suggest that the RECQL gene plays a negligible role in breast cancer predisposition in Pakistan." (PMID 33342430, 2020). "RECQL plays an important role in DNA repair, and is a plausible candidate breast cancer susceptibility gene." (PMID 30610487, 2019). "RECQL-encoded RecQ helicase-like protein is a DNA helicase which plays a vital role in the DNA damage response, and the mutation of RECQL has been suggested as a plausible candidate breast cancer susceptibility gene." (PMID 31426369, 2019). "In 2015, two independent studies provided initial evidence for a novel breast cancer susceptibility gene, RECQL, a DNA helicase which plays an important role in the DNA damage response." (PMID 30610487, 2019). "The allelic variant c.1667_1667+3delAGTA in the RECQL gene is described as a founder mutation in the studied population from Poland, with a frequency of 0.23% in the group of unselected breast cancer cases and 0.04% in the control group with OR = 5.4." (PMID 31312277, 2019). "In 2015, two independent research groups who used different screening strategies to search for new cancer predisposition genes, published evidence suggesting that RECQL is a novel breast cancer susceptibility gene." (PMID 30610487, 2019). "The observation that genes encoding other components of this network are known to act as breast cancer susceptibility genes pointed towards the significance of RECQL as a potential breast cancer susceptibility gene." (PMID 30610487, 2019). "In summary, in this study we found that the low RECQL expression is strongly associated with poor prognosis in breast cancer." (PMID 29914420, 2018). "At present, RECQL was demonstrated as a moderate breast cancer susceptibility gene and a tumor suppressor." (PMID 29914420, 2018). "In order to estimate individual breast cancer risk for carriers of mutations in RECQL and FANCM, very large sample sizes and family based studies are required." (PMID 29351780, 2018). "In this study, we investigated the association between RECQL expression level and survival in patients with breast cancer." (PMID 29914420, 2018). "The results from the cohort 1 showed that RECQL mRNA expression level was significantly associated with survival of breast cancer patients." (PMID 29914420, 2018).
breast cancer (continued). "FANCM and RECQL have recently been reported as breast cancer susceptibility genes and it has been suggested that they should be included on gene panel tests for breast cancer predisposition." (PMID 29351780, 2018). "In this study, we investigated the association between RECQL mRNA and protein expression and survival of breast cancer in two independent cohorts." (PMID 29914420, 2018). "RECQ1 (also known as RECQL or RECQL1) was recently identified as a breast cancer susceptibility gene." (PMID 29100281, 2017). "In total, we found 15 germline variants in the RECQL gene in the 448 familial breast cancer patients (including the nine index cases for whole-exome sequencing)." (PMID 25945795, 2015). "In total, we found nine index cases carried a pathogenic mutation in the RECQL gene among the 448 BRCA-negative familial breast cancer patients." (PMID 25945795, 2015). "The prevalence of the RECQL germline mutations was significantly higher in familial breast cancer patients than in the controls (9/448 vs. 1/1,588; the Fisher exact test, P = 9.14×10–6)." (PMID 25945795, 2015). "Here, we are the first to report that RECQL is a potential breast cancer susceptibility gene and that germline mutations in the RECQL gene are associated with predisposition to breast cancer." (PMID 25945795, 2015). "Taken together, 9 out of 448 BRCA-negative familial breast cancer patients carried a pathogenic mutation of the RECQL gene compared with one of the 1,588 controls (P = 9.14×10-6)." (PMID 25945795, 2015). "Our findings suggest that RECQL is a potential breast cancer susceptibility gene and that mutations in this gene contribute to familial breast cancer development." (PMID 25945795, 2015). "Therefore, this study assessed RECQL mutations and their relationships with clinicopathological and epidemiological characteristics in Chinese women with breast cancer." (PMID 38439896, 2024). "We found that a RECQL mutation is a susceptibility factor for breast cancer." (PMID 38439896, 2024). "Moreover, of the 58 patients with RECQL mutations, 19 had a familial genetic background, 31 had sporadic breast cancer, and eight had missing family history in-formation." (PMID 38439896, 2024). "We have previously shown that germ-line mutations in RECQL are extremely rare and may increase the risk of developing breast cancer." (PMID 38134458, 2023). "Other genes with moderate, low, or uncertain penetrance that have been implicated in breast cancer, RECQL, RAD51B, ERCC3, MRE11A, RAD51D, BARD1, and NBN, had a yield of 0.3% (n = 7), 0.3% (n = 7), 0.3% (n = 6), 0.3% (n = 6), 0.2% (n = 4), 0.2% (n = 4), and 0.1% (n = 3), respectively." (PMID 35971132, 2022). "Interestingly, one of the identified breast cancer–associated variants in RECQL altered the amino acid residue proximal to the RECON syndrome RECQL mutation." (PMID 35025765, 2022). "Other genes: Pathogenic variants in BRIP1, RAD51C, RAD50, NBN, STK11, and RECQL may also confer some level of breast cancer risk." (PMID 34439109, 2021). "The important role of RECQL in the DNA damage response raises the possibility that identification of RECQL mutations might have potential therapeutic implications for women with breast cancer." (PMID 30610487, 2019). "Furthermore, variants of CHEK2 (1100delC, IVS2 + 1G/A, del5395bp, and I157T), PALB2 (509_510delGA and 172_175delTTGT) and RECQL (c.1667_1667 + 3delAGTA) are also associated with breast cancer in the Polish population." (PMID 29678143, 2018). "Moreover, a mutation in the RECQL gene is associated with a 5.5-fold increase in the risk of breast cancer in Poland." (PMID 29678143, 2018). "Finally, our results indicate that RECQL (RecQ helicase-like) is a novel breast cancer susceptibility gene." (PMID 25945795, 2015).
breast cancer (continued). "In total, nine germline mutations in the RECQL gene in the nine familial breast cancer patients were identified as pathogenic, including three nonsense mutations (L128X, W172X and Q266X), one splice-site mutation (395-2A>G) and five missense mutations (A195S, R215Q, R455C, M458K and T562)." (PMID 25945795, 2015). "To determine the germline mutations in the RECQL gene in an additional cohort of familial breast cancer patients, we screened the entire coding region of RECQL gene using Sanger sequencing assays in 439 familial breast cancer patients without BRCA1/2 mutations." (PMID 25945795, 2015). "The 2.0% pathogenic mutation rate of the RECQL gene in familial breast cancer patients is remarkable and may be suitable for screening the mutations in BRCA1/2- negative breast cancer patients." (PMID 25945795, 2015). "Here, we are the first to report that mutations in the RECQL gene are associated with predisposition to breast cancer and this finding may have potential clinical implications and raise research questions about RECQL." (PMID 25945795, 2015). "We thus hypothesized that RECQL deficiency may be an early event during breast cancer pathogenesis." (PMID 38134458, 2023). "Given the potential role for RECQL in transcriptional regulation, we speculated that RECQL deficiency in breast cancer will not only promote genomic instability but will also lead to global transcriptomic alterations that could adversely influence its pathology." (PMID 38134458, 2023). "These indicated that RECQL may associate with malignant phenotype in breast cancer." (PMID 29914420, 2018). "Therefore, mutations in the RECQL gene can lead to breast cancer tumorigenesis." (PMID 25945795, 2015). "Single PVs were identified in other genes associated with breast cancer risk, BRIP1 (c.2392C>T; p.Arg798Ter), RECQL (c.1667_1667+3delAGTA; p.)?" (PMID 33758026, 2022). "There are twenty recurrent mutations in six breast-cancer-predisposing genes in Poland (BRCA1, BRCA2, CHEK2, PALB2, NBN, and RECQL)." (PMID 32824581, 2020). "On the contrary, it has also been shown that RECQL is highly expressed in various tumors, such as multiple myeloma, glioblastoma, ovarian cancer, and breast cancers." (PMID 32820027, 2020). "In 2015, the RecQ Like Helicase (RECQL) gene was identified in West European and East Asian populations as a candidate breast cancer susceptibility gene." (PMID 33342430, 2020). "We genotyped 2464 women with breast cancer diagnosed below age 41 years for twenty recurrent germline mutations in six genes, including BRCA1, BRCA2 CHEK2, PALB2, NBN, and RECQL." (PMID 32824581, 2020). "In our previous study, twenty recurrent mutations were found in six breast-cancer-predisposing genes (BRCA1, BRCA2, CHEK2, PALB2, NBN, and RECQL) in Polish breast cancer patients." (PMID 32824581, 2020). "Large-scale case control studies revealed a number of moderate risk - low frequency breast cancer alleles of the PALB2 and RECQL genes." (PMID 31312277, 2019). "As for most established breast cancer susceptibility genes, RECQL (RECQ1) encodes a protein, functioning in DNA repair." (PMID 31312277, 2019). "We found that breast cancer patients with low RECQL expression had a worse survival than those with high level." (PMID 29914420, 2018). "RECQL was overexpressed in multiple myeloma and ovarian cells, but RECQL expression was similar in breast cancer cell (MCF 7) relative to normal cells." (PMID 29914420, 2018). "Therefore, our team used second-generation sequencing to detect whole-exon susceptibility gene mutations and mutations in four breast cancer susceptibility genes (BRCA1, BRCA2, PALB2, and RECQL) in Chinese women." (PMID 38439896, 2024). "Of the 2,075 breast cancer patients without RECQL mutations, 420 had a familial genetic background, and 1,652 had sporadic breast cancer." (PMID 38439896, 2024). "Emerging data indicates a role for RECQL in breast cancer pathogenesis." (PMID 38134458, 2023).